SLX1A (structure-specific endonuclease subunit SLX1A)
Description:
Catalytic subunit of the SLX1-SLX4 structure-specific endonuclease that resolves DNA secondary structures generated during DNA repair and recombination. Has endonuclease activity towards branched DNA substrates, introducing single-strand cuts in duplex DNA close to junctions with ss-DNA. Has a preference for 5'-flap structures, and promotes symmetrical cleavage of static and migrating Holliday junctions (HJs). Resolves HJs by generating two pairs of ligatable, nicked duplex products.
Synonyms: GIYD1
Tractability: No criterion of Open Targets' tractability assessment is met for any kind of drug.
Gene: Protein-coding gene on chromosome 16 (30,193,875 to 30,197,566, forward strand). Ensembl gene ENSG00000132207.
Subcellular location: Nucleus
Subcellular location (Human Protein Atlas): Nucleoplasm
Pathways (Reactome):
DNA Repair: Fanconi Anemia Pathway; Resolution of D-loop Structures through Holliday Junction Intermediates
Gene Ontology:
Molecular function: 5'-flap endonuclease activity; crossover junction DNA endonuclease activity; protein binding
Biological process: DNA double-strand break processing involved in repair via single-strand annealing; DNA repair; double-strand break repair via homologous recombination; negative regulation of telomere maintenance via telomere lengthening; t-circle formation; telomere maintenance via telomere lengthening; telomeric D-loop disassembly; DNA replication; positive regulation of t-circle formation; DNA recombination; regulation of telomere maintenance
Cellular component: nuclear chromosome; nucleoplasm; Slx1-Slx4 complex; nucleus
Genetic constraint (gnomAD): Loss-of-function variants: 0 observed, 2.76 expected, observed/expected ratio (o/e) 0, 90% interval 0 to 1.06. That is too few expected variants to judge how well the gene tolerates losing a copy. Missense variants: 0 observed, 20.48 expected, observed/expected ratio (o/e) 0, 90% interval 0 to 0.15. Synonymous variants: 0 observed, 4.36 expected, observed/expected ratio (o/e) 0, 90% interval 0 to 0.69.
Homologues: Orthologues: chimpanzee SLX1A (99% identical), dog SLX1A (81% identical), guinea pig Slx1a (77% identical), mouse Slx1b (76% identical), rat Slx1b (62% identical), tropical clawed frog slx1a (50% identical), zebrafish slx1b (44% identical), Drosophila melanogaster slx1 (40% identical), Caenorhabditis elegans slx-1 (35% identical). Paralogues in human: SLX1B (100% identical).
Diseases named in the same sentence as SLX1A in open-access papers:
SLX1A is named in the same sentence as 4 diseases in open-access papers, as found by Europe PMC text mining. Sharing a sentence is not in itself a finding about the gene and the disease. The quoted sentences say what the papers report.
bladder cancer (1 paper, 2018). "In bladder cancer, 3 out of these identified 39 DDR genes, i.e., SLX1A, ERCC1, and RBBP8, exhibited hypermethylation over 15%." (PMID 29445424, 2018).
SLX1A also shares sentences with these, for which no sentence is quoted: cancer (1 paper); Fanconi anemia (1); tumour (1).